IL1B (interleukin 1 beta)
Diseases named in the same sentence as IL1B in open-access papers (continued):
Sharing a sentence is not in itself a finding about the gene and the disease.
tauopathy (23 papers, 2014 to 2026). Neurodegenerative disorders involving deposition of abnormal tau protein isoforms (tau proteins) in neurons and glial cells in the brain. "Neutralizing pathological tau with a vaccine or genetic deficiency of inflammasomes reduced IL-1β activation, neuroinflammation, tau hyperphosphorylation, and improved memory in different mouse models of tauopathy." (PMID 41353558, 2025). "Caspase-1 knockout reduced the viability of BV2 microglia, but not LDH release, and increased IL-1β levels, which not only affected the function of sevoflurane but also indicated that microglia-derived IL-1β causes tauopathy deterioration, as observed with other tau kinases." (PMID 35127716, 2021). "In addition, upregulation of IL-1β transcription in microglia of old mice and in blood cells of aging humans and demented patients with tauopathy has been revealed to be associated with selective hypomethylation of IL-1β promoter." (PMID 34630044, 2021). "Remarkably, P2rx7 disruption in tauopathy model mice not only reduced the expression of oxidative stress-associated genes but also decreased the conversion of microglia into the InfM state, which is characterized by the expression of Nlrp3, Il1b, and other proinflammatory cytokines." (PMID 40678243, 2025). "Reports implicating the NLRP3 inflammasome in the progression of tauopathy hint at a possible role of IL-1β, since cleavage of pro-IL-1β is downstream of NLRP3 activation." (PMID 41191631, 2025). "Inhibition of IL-1β signaling in animal models of tauopathy reduced p-tau, ameliorated cognitive dysfunction and downregulated MAPK activation." (PMID 40349043, 2025). "The authors also showed that p-Taues accumulation concurred with elevated ASC and IL-1β levels in postmortem brains of tauopathies patients." (PMID 37189617, 2023). "Neuroinflammation can amplify itself by increasing tauopathy and Aβ deposition through inflammatory cytokines such as IL-1β, IL-6, and TNF-α." (PMID 36389075, 2022). "Studies using the PS19 mouse model of tauopathy have demonstrated that TREM2 signaling aggravates NFT pathology, associated with pro-inflammatory, Il-1β+ microglia." (PMID 35764973, 2022). "While activation of NLRP3–ASC inflammasome in primary Tauopathy patients remains to be demonstrated, it must be noted that Tau has been detected in microglia, in Tauopathy patients, and IL-1β levels were increased in brains of Tauopathy patients." (PMID 30721409, 2019). "Future studies utilizing pure tauopathy models and tissue samples from primary tauopathies will help elucidate the specific effects of IL-1β on tau-mediated neurodegeneration." (PMID 28662669, 2017). "Arguably the most prominent cytokine consistently upregulated in AD and related tauopathies is IL-1β." (PMID 28662669, 2017). "Nevertheless, IL-1β is clearly a pivotal cytokine capable of driving chronic gliosis, influencing tauopathy progression and impacting tau-induced neurodegeneration." (PMID 28662669, 2017). "Indeed, we expected a greater induction of IL-1β by tauopathy based on reports from other inflammatory conditions." (PMID 41191631, 2025). "In mouse models of AD-like pathology, tauopathy alone induces an IL-1β response." (PMID 41191631, 2025). "Similarly, we observed an age-dependent increase in Il1b mRNA in the rTg4510 mouse model of tauopathy as well as an increase in IL-1β protein at six months of age." (PMID 41191631, 2025). "However, Tau was detected in microglia in Tauopathy brains, and IL-1β has been shown to be increased not only in brains of AD patients, but also in Tauopathy patients, in line with inflammasome activation in patients." (PMID 30721409, 2019). "Notably, the absence of fractalkine signaling ameliorates Aβ plaque burden in APPPS1 transgenic mice, but exacerbates intraneuronal tau pathology in hTau mouse model of pure tauopathy, even though both events likely occur via dysregulation of IL-1β-p38 MAPK signaling pathway." (PMID 30253780, 2018).
tauopathy (continued). "Genetic deletion of C3 in tauopathy mice mitigated neurodegeneration and neuroinflammation through the reduction of STAT-dependent cytokine production, including IL-1β." (PMID 40349043, 2025). "Hippocampal expression of IL-1β was shown to robustly reduce plaques in the APP/PS1 model and 3xTg-AD model but worsened tauopathy in the 3xTg-AD model." (PMID 35897046, 2022). "Hippocampi and amygdalae from 3x Tg-AD linalool-treated mice also showed a large reduction in extracellular β-amyloidosis, tauopathy, astrogliosis, and microgliosis, as well as pro-inflammatory marker levels of p38 MAPK, NOS2, COX2 and IL-1β." (PMID 33669787, 2021). "In addition to regulation of tauopathy, we found that HSF1 overexpression attenuated production of inflammatory molecules such as iNos, Cxcl10, and Il-1β and prevented leukocyte attachment and infiltration, which is a hallmark of vascular inflammation." (PMID 30884523, 2019). "Furthermore, our data suggest that reduced canonical IL-1β signaling may not be responsible for the observed effects of NLRP3 disruption in mouse models of tauopathy." (PMID 41191631, 2025).
Ureteral obstruction (23 papers, 2012 to 2025). Obstruction of the flow of urine through the ureter. "Renal inflammation has been connected to the activation of the NLRP3 inflammasome and the overproduction of IL-1β in a unilateral ureteral obstruction mouse model." (PMID 35708451, 2022). "Here, human embryonic kidney epithelial cells (HKC) and unilateral ureteric obstruction (UUO)-induced RIF models on SD rats were used to investigate the functions of TIR8 involving IL-1β-induced EMT." (PMID 33945104, 2021). "Consistent with our findings, previous studies have shown that garcinol suppressed cytokine production in lipopolysaccharide-stimulated microglia, IL-1β-treated chondrocytes, and kidneys from mice subjected to unilateral ureteral obstruction." (PMID 33327548, 2020). "Furthermore, melittin has been shown to reduce TNF-α and IL-1β expression in chronic kidney injury models, such as unilateral ureteral obstruction, highlighting its broad anti-inflammatory efficacy across different etiologies of renal injury." (PMID 41301702, 2025). "For example, ureteral obstruction caused a significant upregulation of the mRNA expression of TNF-α, PAI-1, IL-6, and IL-1β (2.22 ± 0.47 vs. 1.03 ± 0.11, 5.38 ± 0.87 vs. 1.02 ± 0.10, 10.35 ± 1.42 vs. 1.00 ± 0.21 and 1.55 ± 0.07 vs. 0.99 ± 0., respectively, p < 0.05 for all)." (PMID 39457599, 2024). "In the absence of MFAP4, downregulation of pro-inflammatory cytokines (IL-1β and TNF-α) and concurrent inhibition of NF-κB signaling pathway activation can mitigate the inflammatory response induced by unilateral ureteral obstruction." (PMID 39508749, 2025). "In a unilateral ureteral obstruction (UUO) mouse model of hypoxic CKD, IL-1RI expression is induced in tubular and interstitial cells, with IL-1β/IL-1RI pathway activation in tubular epithelial cells mediating progressive tubulointerstitial fibrosis." (PMID 39890773, 2025). "In a unilateral ureteral obstruction mouse model, that it suppressed expressions of pro‐inflammatory factors including NF‐κB, COX‐2, and IL‐1β." (PMID 39501714, 2024). "A study showed that the expression of IL-1β, IL-6, IL-18, and TNF-α in peripheral blood and renal tissues of rats with unilateral ureteral obstruction was significantly reduced by DSF." (PMID 35563653, 2022). "For instance, reduced expression and maturation of IL-1β, IL-18 and caspase-1 activation and reduced tubular damage and fibrosis in an NLRP3 knockout unilateral ureteral obstruction (UUO) model was observed." (PMID 34680443, 2021). "In conclusion, glomerular miR-21 expression is elevated following unilateral ureteral obstruction, wherein it interacts with TLR8 in podocytes and induces production of downstream cytokines (Il1b and Il6) suggesting activation of NF-κB pathway." (PMID 33552064, 2020). "By qRT-PCR, we found that the inflammatory markers TNF-α, IL-1β, and ICAM-1 were markedly elevated following 7-day ureteral obstruction, and such increments were robustly abolished or attenuated by rotenone administration." (PMID 25140114, 2014). "We first tested the ability of ibrutinib to prevent renal injury and progression toward fibrosis in C57BL/6 mice submitted to unilateral ureteric obstruction (UUO), a model of rapidly progressive kidney fibrosis characterized by increased mRNA expression of Il1b and Nlrp318." (PMID 34099830, 2021). "mRNA expression of IL1α, IL1β and IL18 but not of TNFα increased in response to ureteral obstruction (D and C correspondingly)." (PMID 37553369, 2023).
diabetic cardiomyopathy (22 papers, 2017 to 2025). Diabetic cardiomyopathy is a disorder of the heart muscle in people with diabetes. "Metformin increased pAMPK and decreased caspase-1 and IL-1β expression, thereby improving the symptoms of diabetic cardiomyopathy." (PMID 34122131, 2021). "BMP-7 treatment showed a significant reduction (p < 0.001) in the expression of IL-1β, and IL-18 compared to the diabetic cardiomyopathy." (PMID 34685620, 2021). "As reported in a previous study, phosphorylation of AMPK (pAMPK) was reduced in diabetic cardiomyopathy mice and high glucose-treated cardiomyocytes, and inflammation and pyroptosis markers such as caspase-1 and IL-1β were significantly increased." (PMID 34122131, 2021). "In diabetic cardiomyopathy, IL-1β promotes cardiomyocyte apoptosis by inducing endoplasmic reticulum stress." (PMID 31681001, 2019). "A study reported that the NLRP3 inflammasome contributed to the development of diabetic cardiomyopathy via ROS‐induced caspase‐1 and IL‐1β activation, which are the effectors of the NLRP3 inflammasome." (PMID 29314607, 2018). "Furthermore, Sun and Ding70 proposed that diabetic cardiomyopathy is an inflammatory disease exacerbated by NLRP3 inflammasome-mediated release of IL-1β and IL-18." (PMID 38532054, 2024). "Sullivan and collaborators hypothesize that alteration in expression in ghrelin receptor observed in diabetic cardiomyopathy could be a consequence of upregulation of inflammatory factors such as IL-1β, IL-6." (PMID 31375017, 2019). "Recent evidence has shown that high glucose could promote NLRP3 inflammasome-mediated collagen synthesis, leading to caspase 1 activation and IL-1β secretion, which ultimately contribute to cardiac fibrosis in diabetic cardiomyopathy." (PMID 31354519, 2019). "In this regard, statins as rosuvastatin have also exhibited beneficial proprieties against diabetic cardiomyopathy through inhibition of NLRP3 inflammasome and mature IL-1β, via suppression of the MAPKs activation." (PMID 28659798, 2017). "Studies unveiled that inhibiting p38MAPK activity in diabetic cardiomyopathy mouse models effectively lowers the levels of inflammatory cytokines such as TNF-α, IL6, IL1-β, and TGF-β1 in myocardial tissue, thus improving the left ventricular function of DCM mice." (PMID 40373162, 2025). "They proposed that a chronic training intervention is an effective preventive and curative approach to ameliorate diabetic cardiomyopathy by modulating the NLRP3 inflammasome and subsequently reducing inflammation, a finding confirmed by our results (i.e., decreased IL1β and increased IL10 levels)." (PMID 38532054, 2024). "In this study, we found that miR-223-3p, as a regulator of the pyroptosis molecule NLRP3, is downregulated in the myocardium of diabetic cardiomyopathy mice, but significantly increased after MSC treatment, thereby reducing the protein levels of NLRP3, Caspase-1, GSDMD, and IL-1β." (PMID 38956716, 2024). "Its knockdown improves cardiac contractile function and reduces inflammatory factors such as TNF-α, IL-6 and IL-1β in the diabetic myocardium, thus suggesting that MALAT1 may be involved in the inflammatory response to diabetic cardiomyopathy." (PMID 37396588, 2023). "In addition, a glucocorticoid (methylprednisolone) treatment reduced expression of TLR4/NF-κB signaling and IL-1β, IL-6, TNF-α, and ICAM-1 on T1DM-induced diabetic cardiomyopathy with I/R injury." (PMID 28659798, 2017). "Interestingly, in T1DM-induced diabetic cardiomyopathy, administration of an anti-TNF-α monoclonal antibody lessen cardiac TNF-α and IL-1β expression in correlation with cardiac collagen-I and -III content, and improvement of left-ventricle function." (PMID 28659798, 2017).
diabetic cardiomyopathy (continued). "(2016) investigated the potential role of DOE in diabetic cardiomyopathy and found that DOE downregulated the activities of TNF-α and IL-1β, indicating that DOE might have protective potential for human against oxidative damage via inhibition of several pro-inflammatory factors." (PMID 32657196, 2020).
hemorrhage (22 papers, 2010 to 2025). Loss of blood from the vascular compartment to the exterior or into nonvascular body space as a result of rupture or severance of the blood vessels. "In our IVH model, the hemorrhage likely provided a strong priming signal, leading to the accumulation of pro-IL-1β within the cells of the periventricular region." (PMID 41270129, 2025). "Our study found that the intervention of ENA reduces the expression of TNF‐α, IL‐1β, and IL‐6 in the tissues around the hematoma lesion after hemorrhage, thereby reducing the inflammatory injury." (PMID 37614117, 2023). "We summarized that SNPs of five inflammatory genes (IL6, APOE, IL1B, IL17A, MMP9) were reported to be associated with bAVM-related hemorrhage." (PMID 37065486, 2023). "Studies have found that nuclear factor‐κB (NF‐κB) in the tissues surrounding hematoma lesion will be activated 13–48 h after hemorrhage, and the expression levels of IL‐1β and TNF‐α increase within 1 day." (PMID 37614117, 2023). "We have considered that IL-1β is also a key element in viral pathogenesis of SFTS which is an acute febrile disease with a tendency for hemorrhage." (PMID 35173184, 2022). "A variety of inflammatory factors, such as TNF-α and IL-1β, are expressed around the hemorrhage area after cerebral hemorrhage." (PMID 35260880, 2022). "In accordance, anti-HMGB1 was previously shown to inhibit IL-1β release after airway endotoxin exposure and in pulmonary injury induced by hemorrhage." (PMID 24342460, 2013). "The post-hemorrhage increase in serum IL-1β levels was suppressed in the FR+Hemorrhage group at all timepoints." (PMID 22253904, 2012). "Other surrogate markers of lung damage, such as lung proinflammatory cytokines (mainly IL-1β) and vascular permeability, were also exacerbated by hemorrhage in the present study." (PMID 20949109, 2010). "This led to the identification of statistically significant association between bAVM-related hemorrhage and twelve heritable variants of seven genes (IL6, APOE, IL1B, IL17A, MMP9, EPHB4, and VEGFA) involved in the inflammatory and angiogenic signaling pathways." (PMID 37065486, 2023). "However, in a rat filament model of SAH, it was shown that heme upregulated the expression of HO-1 around the hemorrhage site and IL-1α, which was confirmed in-vitro by application of heme to organotypic slice cultures preferentially releasing IL-1α over IL-1β." (PMID 30011792, 2018). "Since it has been demonstrated that treatment with P2X7 receptor antagonist and IL-1β antibody could also reduce thalamic hemorrhage-induced microglia aggregation, neuronal excitability and allodynia phenomena in CPSP rats, a common upstream regulation by HIF-1α-SDF1-CXCR4 signaling might be shared." (PMID 28785202, 2017). "For example, CUR alleviates neuronal apoptosis and neuroinflammation induced by cerebral haemorrhage by inhibiting the JAK1/STAT1 pathway and inhibits IL-1β-induced chondrocyte apoptosis by activating autophagy and inhibiting the NF-κB pathway." (PMID 39000093, 2024). "Patients with haemorrhage-hepatitis syndrome had lower concentrations of IFN-α, IFN-λ2/3, IL-1β and IFN-γ and higher levels of IP-10, IFN-λ1, IL-6, IL-10, TNF-α and GM-CSF." (PMID 37090924, 2023). "In the ipsilateral region (around the hemorrhage), TNF-α was significantly increased on day 3, IL-1β on days 1 and 3, and IL-6 on day 1 after ICH compared to the sham group." (PMID 37190062, 2023). "The Nlrp3 inflammasome, IL-1β, and TNF-α contributed to inflammation, coagulation defects, and hemorrhage." (PMID 33717109, 2021). "The increase in serum levels of proinflammatory cytokines IL-1α, IL-1β, IL-6, and TNF-α in the groups submitted to hemorrhage agrees with findings in other studies showing greater production of these inflammatory mediators in renal injury." (PMID 29535870, 2018). "An increase in serum IL-1β contributes for the development of SIRS and organ dysfunction following hemorrhage." (PMID 25830444, 2015).
hemorrhage (continued). "Whether other cytokines (e.g., IL-1β and nitric oxide) as well as chemokines induced by the activated NF-κB and ERK1/2 pathways mediate the role of Fgr in hemorrhage-induced thalamic pain is unknown and open to further study." (PMID 33055425, 2020).